TIGIT (T cell immunoreceptor with Ig and ITIM domains)
Diseases named in the same sentence as TIGIT in open-access papers (continued):
Sharing a sentence is not in itself a finding about the gene and the disease.
cancer (continued). "In NK cells, it has been shown that TIGIT blockade prevents NK cell exhaustion and induces potent anti-tumor immunity, suggesting that its targeting might have anti-cancer therapeutic potential." (PMID 36015348, 2022). "However, under long-term antigen (such as malignant tumor) stimulation, the continuous expression of TIGIT leads to the exhaustion of T cell function, resulting in the deficiency of immune function." (PMID 36561512, 2022). "Furthermore, T cell immunoreceptor with Ig and ITIM domains (TIGIT), a novel co-inhibitory receptor of T cell and natural killer cell activity, has become a recent popular target in cancer immunotherapy." (PMID 35493449, 2022). "In 33 cancer types, TIGIT and HAVCR2 expression had positive correlations with GBP1 expression." (PMID 35222540, 2022). "Furthermore, CCNA2 is positively associated with expressions of immune checkpoints (CD274, CTLA4, HAVCR2, LAG3, PDCD1, and TIGIT) in most cancer types." (PMID 35480884, 2022). "CCNA2 was positively correlated with expressions of CD274, CTLA4, HAVCR2, LAG3, PDCD1, and TIGIT in most cancer types, which indicated the CCNA2 expression may act as a marker after immunotherapy." (PMID 35480884, 2022). "Interestingly, these receptors are over-expressed in several types of cancers, inducing T cell suppression by interacting through the axis TIGIT/PVR in DCs." (PMID 36015348, 2022). "Additionally, in PD-L1-positive NSCLC cancer patients, the combined PD-L1/TIGIT inhibition (atezolizumab + tiragolumab) leads to greater clinical benefits in comparison with PD-L1 inhibition alone, despite having similar toxicity profiles." (PMID 36231109, 2022). "Their wide expression suggests that TIGIT interaction with PVR could hamper the anti-cancer immune surveillance." (PMID 36544779, 2022). "It has been shown that TIGIT suppresses immune cell responses against cancer." (PMID 35844584, 2022). "Additionally, studies have indicated an association between clinical immune therapy effects and prognoses and the expression of immune checkpoint genes, including CTLA-4 and TIGIT, in various cancers." (PMID 36614956, 2022). "TIGIT expression is upregulated on a multitude of human cancers, including HPV+ malignancies." (PMID 36211806, 2022). "Notably, checkpoint pathways with a known role in the APC/Th interplay, such as TIM-3, LAG-3, and TIGIT, are among the most promising checkpoint targets in the cancer immunotherapy pipeline." (PMID 36389687, 2022). "Consistent with previous reports, patients with cancer showed immune exhaustion phenotype as indicated by increased cell-surface expression of PD-1, TIGIT, and Tim-3 but reduced CD28 expression on CD8+ T cells and Vγ9Vδ2+ T cells, while cell surface CTLA-4 was barely detectable." (PMID 35318258, 2022). "Besides, our research manifested the correlation of SLC7A11 with 8 IC genes, namely CD274 (also known as PD-L1), HAVCR2, LAG3, SIGLEC15, PDCD1LG2, CTLA4, PDCD1, and TIGIT in 33 cancer types." (PMID 36267158, 2022). "Moreover, we have previously confirmed that MWA combined with TIGIT blockade exerts synergistic effects against cancer in contrast to MWA or TIGIT blockade alone." (PMID 36180876, 2022). "In addition to the well-known immune checkpoint PD1, TIGIT has also been reported as a potential target for the treatment of malignant tumors." (PMID 35875070, 2022). "Taken together, these data suggest that TIGIT might represent a promising target for next-generation cancer immunotherapy." (PMID 36231109, 2022). "Recently, a novel ligand for TIGIT was discovered on cancer cells." (PMID 35634292, 2022). "Cancer immunotherapy targeting the TIGIT/PVR pathway is currently facing challenges." (PMID 36377656, 2022). "TIGIT has been observed increased expression in immune cells infiltrated in cancer." (PMID 35433470, 2022). "Several studies have shown an overexpression of TIGIT in different types of cancer." (PMID 35465350, 2022).
cancer (continued). "Furthermore, TOP2A was positively associated with expression of immune checkpoints (CD274, CTLA4, HAVCR2, LAG3, PDCD1 and TIGIT) in most cancer types." (PMID 35778520, 2022). "The immunomodulatory receptor TIGIT is an emerging ICI for cancer immunotherapy." (PMID 35804895, 2022). "Rodent and in vitro cancer models showed that targeting the immune checkpoint molecule TIGIT might restore T cell function." (PMID 36133956, 2022). "Additionally, these cancer cells suppressed CD8+T cell metabolism via CD155/TIGIT signaling, mediated by down-regulation of the AKT/mTOR signaling pathway." (PMID 35433470, 2022). "TIGIT expression in cancer cells may be beneficial for a potential utility in MTC and a subset of high-grade TC, especially ATC therapy." (PMID 35971106, 2022). "Anti-TIGIT monotherapy has shown encouraging results in the treatment of diverse cancers, and combining TIGIT blockade with the inhibition of adenosine production, restores NK cell-mediated AML cell killing, which might enhance treatment efficacy." (PMID 36713558, 2022). "In addition, AP3S1 was positively correlated with most immunosuppressive genes, including PD-1, PD-L1, CTLA4, LAG3 and TIGIT in most cancer types." (PMID 35874816, 2022). "Like these carcinomas, TIGIT mRNA expression was upregulated in ATCs." (PMID 35971106, 2022). "Interestingly, DTC components (PTC and FTC) were devoid of TIGIT in composite ATC carcinomas, although the composite PTC components displayed high-grade features, tall cell with hobnail structure." (PMID 35971106, 2022). "Antibodies targeting TIGIT/PVR pathway have achieved good effects in cancer treatment." (PMID 33557880, 2021). "TIGIT could enhance T-cell function by inhibiting PVRIG, so TIGIT-PVRIG pathways play a vital role in human cancers." (PMID 34901000, 2021). "Blockade of TIGIT/PVR is considered as a promising strategy in cancer immunotherapy." (PMID 33557880, 2021). "Dual blockade of TIGIT and PD-1 resulted in the restoration of T-cell immunity in preclinical settings and provided a rationale for combination with these agents as a feasible anti-cancer therapeutic strategy." (PMID 34025438, 2021). "Our results showed that the expression of TIGIT was upregulated in most of the cancer types." (PMID 34795387, 2021). "The depletion of CD8+ T cells eliminated the therapeutic efficacy of VV-α-TIGIT, which was accomplished by the reduction of lymphocyte subsets (T, NK, NKT) and IFN-γ secretion, indicating that the activation of CD8+ T cells has an indispensable role in anti-cancer immunity induced by VV-α-TIGIT." (PMID 33581644, 2021). "Therefore, blockade of TIGIT or the TIGIT-ligand interaction represents a potentially promising cancer therapy." (PMID 34433460, 2021). "Dual-target small molecule inhibitor (SMI) co-targeting the CD47/SIRPα and TIGIT/PVR may also exert exciting effects in the cancer immunotherapy." (PMID 34068552, 2021). "In various cancers, TIGIT expression is greatly increased alongside the expression of PD-1 on TILs." (PMID 34507594, 2021). "Therefore, the development of other types of drugs targeting TIGIT/PVR pathway is essential for cancer intervention and treatment." (PMID 33557880, 2021). "TIGIT has emerged as a promising target for next generation cancer immunotherapy." (PMID 33670993, 2021). "Our results found certain positive and negative correlations between DNMTs and TIGIT expression in different cancer types, suggesting DNA methylation may also participate in the modulation of TIGIT, as previous studies reported." (PMID 34795387, 2021). "Immunostainings of CRC samples from short-term survivors show a strong expression of TIGIT in intra-tumoral immune cells, scattered within the cancer and lymphoid structures, but also in fibroblast-like stromal cells, resulting in a robust barrier against immune attack." (PMID 34975867, 2021). "A large number of data supports the hypothesis that blocking TIGIT would promote NK cell functions against cancer." (PMID 34503073, 2021).
cancer (continued). "PD-1 has been found expressed in cells with an exhausted phenotype whereas TIGIT has been associated with selective Th1 and Th17, but not Th2 suppression, thus both molecules are relevant to cancer-related Th responses." (PMID 34025655, 2021). "Thus, TIGIT has been shown play a protective role in autoimmunity, and it negatively regulates the immune response to cancer by inducing T cell exhaustion." (PMID 34100383, 2021). "In addition, based on the GEPIA2 dataset, we verified that TIGIT expression had a forceful positive correlation with advanced cancer stages in KIRC, KIRP and SKCM (p < 0.01)." (PMID 34795387, 2021). "TIGIT plays multiple roles in the inhibition of cancer immunity." (PMID 34025438, 2021). "The anti-TIGIT antibodies for the treatment of cancer and lymphoproliferative disease (tiragolumab) are currently under clinical trials and TIGIT might be attractive as a target for immunotherapy." (PMID 33782477, 2021). "Multiple clinical trials are also ongoing to test whether TIGIT blockade could translate into an actual benefit for patients with cancers (NCT04354246, NCT04150965, NCT04570839)." (PMID 34795387, 2021). "Dual blockade of TIGIT and PD-1 has demonstrated enhanced anti-cancer immunity in several cancers." (PMID 34884723, 2021). "And in 16 types of cancers TIGIT was negatively correlated with the expression of MMR genes." (PMID 34795387, 2021). "However, the association of CD36 expression with CD274 (PDL-1), TIGIT, and TNFRSF25 was cancer type-specific." (PMID 34234847, 2021). "Checkpoint blockade using anti-TIGIT mAbs, alone or in combination with other therapies, may represent a good strategy for cancer therapy in AML." (PMID 32764229, 2020). "Our findings support a model that is suggestive of both T-cell activation as well as myeloid-cell signaling through FcγR engagement in an effective combination anti-cancer treatment of effector function enabled anti-TIGIT antibodies in combination with anti-PD-1." (PMID 33117369, 2020). "Our research provides a promising candidate for cancer immunotherapy based on TIGIT/PVR blockade." (PMID 32894141, 2020). "One common hypothesis is that the simultaneous blockade of TIGIT and PD-1 may represent a novel cancer immunotherapy by enhancing both T and NK cell-mediated immune responses." (PMID 32903786, 2020). "Notably, the blockade of TIGIT has been revealed as a potential promising approach in cancer immunotherapy." (PMID 32903786, 2020). "Similar to the CD28/CTLA-4 pathway, CD96 and TIGIT act as co-inhibitory receptors together with the co-stimulatory receptor CD226, which supports the contention that CD96 and TIGIT could be targeted for cancer immunotherapy." (PMID 32612110, 2020). "We will summarize what is known to date on the expression and function of these checkpoint receptors on NK cells and ILCs, with a particular focus on the recent data that reveal an essential contribution of the blockade of PD-1 and TIGIT on NK cells to the immunotherapy of cancer." (PMID 31105707, 2019). "Moreover, cancer cells induce NK cell exhaustion by stimulating immune checkpoints (PD-1 and TIGIT) on NK cells." (PMID 31619256, 2019). "TIGIT has emerged as a novel inhibitory receptor that can be targeted by mAb and represents a new checkpoint for the development of immunotherapy strategies against cancer." (PMID 31234588, 2019). "Also, PD-1 blockade combined with other checkpoint blockades, such as Tim-3, LAG-3, or TIGIT, significantly reverses T cell dysfunction and enhances antitumor immunity in patients with cancer, compared to individual checkpoint blockade." (PMID 31379886, 2019). "Overall, it can be speculated that in cancer patients the TIGIT/PVRIG pathways are upregulated and represent novel targets for checkpoint blockade immunotherapy." (PMID 31234588, 2019).
cancer (continued). "Our results broaden the knowledge that TIGIT could not only express on immune cells, but also on cancer cells, and this intrinsic expression may deliver inhibitory signals through the interaction with PVR on CD8+ T cells and NK cells." (PMID 30555485, 2018). "In addition, we noticed that the correlation between PD-1 and other immune checkpoints including LAG3, CTLA-4 and TIGIT is different for different types of cancer." (PMID 30607140, 2018). "The blockade of TIGIT/PVR interaction is a promising approach in cancer immunotherapy." (PMID 30555485, 2018). "TIGIT is expressed on CD8+ TILs either alone or together with PD-1 in various human cancer types." (PMID 28443090, 2017). "Furthermore, combined treatment with anti-PD-1 and anti-TIGIT antibodies significantly augments CTL activity against cancer cells." (PMID 26735971, 2016). "Similarly, while anti-TIGIT antibodies have shown remarkable effectiveness in treating solid tumors, the dual blockade of PD-1 and TIGIT has demonstrated superior clinical benefits in cancer treatment." (PMID 40067762, 2025). "The presence of TIGIT on CD8+ T cells and NK cells is associated with a suppressive immune state and the production of cytokines, underscoring its significance in autoimmune diseases and various cancers like acute myeloid leukemia, chronic myelogenous leukemia, lung cancer, and melanoma." (PMID 40777027, 2025). "Since TIGIT is also co-expressed with PD-1 on tumor-antigen-specific T cells and TILs in various cancer patients, co-targeting TIGIT and PD-L1 using bsAb may overcome resistance to anti-PD-L1 therapy and enhance the antitumor benefit in tumors showing a high expression of TIGIT, CD155, and CD112." (PMID 38257366, 2024). "In addition, TIGIT expression represents a sign of T cell exhaustion in several cancers." (PMID 38229100, 2024). "However, the axis PVR/TIGIT signaling between NK cells and cancer cells is bidirectional." (PMID 39511139, 2024). "Consequently, this amplifies the harmful effects of natural killer 226 cells via the interplay of CD92, CD155, and the TIGIT co-inhibitory receptor, which in turn facilitates the cancer-fighting capabilities of EC cells and produces twofold anti-cancer impacts." (PMID 38601753, 2024). "On the contrary, the transmembrane proteins that we will focus on, namely PD-1, CTLA-4, LAG-3, TIM-3, and TIGIT, are involved in the downregulation of a T-cellular immune response, including an anti-cancer immune response, preventing the cytotoxic T cells from killing cancer cells." (PMID 38893211, 2024). "Notably, the enrichment of TIGIT+ Tregs has been detected in various cancer groups." (PMID 37671150, 2023). "Furthermore, there was substantial clonal overlap across clusters, particularly between transitory Teff and TIM-3+ Tex and TIGIT+ Teff populations, consistent with previous literature describing transitory Teff cells as intermediaries to terminal differentiation in cancer and chronic infection." (PMID 36512425, 2023). "Then, three-armed cancer-targeting OAds were developed: OAd-SIRPα-Fc and OAd-Siglec10-Fc, which expressed SIRPα-Fc or Siglec10-Fc, respectively, to target macrophages to restore the phagocytic capabilities of these cells, and OAd-TIGIT-Fc, which secreted TIGIT-Fc to reactivate T cells." (PMID 38016957, 2023). "In pathway analysis and cancer immune correlation analysis, we observed that SRSFs were associated with the activation or inhibition of multiple immune pathways, and were also closely related to the expression of multiple immune checkpoints (LAG3, CD274, CTLA4, TIGIT, PDCD1)." (PMID 38015716, 2023). "If TIGIT and PD-1 are prominent players in oesophageal tissue for controlling immune activation, then targeting both TIGIT and PD-1 in tandem to remove the brakes on anti-cancer immunity may be an effective combination to test in OAC." (PMID 37520544, 2023). "Indeed, TIGIT has recently entered the spotlight as a promising IC target in cancer immunotherapy." (PMID 36291830, 2022).
cancer (continued). "Apart from PD-1, TIGIT blockade could also synergize with other ICBs in cancer immunotherapy." (PMID 36189222, 2022). "TIGIT may play a role in the cancer immunity cycle through its ITIM." (PMID 35729552, 2022). "However, since CD155-TIGIT interaction contributes to cancer resistance to PD-1 blockade, inhibition of TIGIT may be a promising strategy to increase the efficacy of PD-1 blockade therapy, especially to combat PD-1 inhibitor resistant tumors." (PMID 34367161, 2021). "However, NK cell TIGIT expression has been shown to be upregulated in cancer, establishing CD155 as a predominantly inhibitory receptor within the context of GBM and other solid tumors, and rendering it of interest as a potential target for antigen-specific NK cell-based immunotherapy." (PMID 32532329, 2020). "Thus, targeting the TIGIT axis may represent a promising additional tool to revivify NK cell functions in cancer patients." (PMID 29023417, 2017). "As one of our primary goals was to investigate the potential importance of ICRs in γδ T cell subsets in health and in cancer, we additionally assessed expression of PD-1, TIM-3, LAG-3, TIGIT and CTLA-4 by flow cytometry in all patients." (PMID 41310392, 2026). "The correlation between SLC2A1 expression and eight immune checkpoints (CTLA4, PDCD1, TIGIT, LAG3, CD274, HAVCR2, PDCD1LG2, and SIGLEC15) was further investigated across multiple cancer types." (PMID 40824962, 2025). "T-cell immunoreceptor with Ig and ITIM domains (TIGIT) and lymphocyte-activation gene 3 (LAG-3) are newly identified immune checkpoint molecules that play critical roles in immune suppression in various cancers." (PMID 40861435, 2025). "TIGIT, through binding to CD155, inhibits the CD226 signal, thus promoting cancer cell growth and metastasis by blocking the function of CD8+ T cells and NK cells." (PMID 40362333, 2025). "TIGIT is expressed on cytotoxic and helper T cells, Tregs cells, and NK cells, while its main ligand CD155 (PVR) is expressed on MDSCs and cancer cells." (PMID 40003864, 2025). "Further analyses showed that these high HLA‐DR+ cancer cell tumors exhibited elevated levels of LAG3, TNFRSF9, CTLA4, PDCD1, TIGIT, ITGB2, and GZMB." (PMID 40464412, 2025). "Previous studies have highlighted the differential expression patterns of HAVCR2, TIGIT, LAG3, LAYN, and CXCL13, showing strong correlations with survival outcomes across multiple cancer types." (PMID 40076932, 2025). "For instance, increased expression of inhibitory checkpoints such as LAG-3, TIGIT, and TIM-3 has been documented in various cancers." (PMID 40805205, 2025). "Further investigation of anti-CCR8 RIT as a potential cancer-agnostic agent and its combinations with other immunotherapy agents such as anti-PD-1, LAG3 or TIGIT is warranted." (PMID 41035646, 2025). "TIGIT and CD155 expression has been proposed as a marker of prognosis in several cancers, and in 2021, the U.S. Food and Drug Administration approved the first commercially available anti-TIGIT antibody tiragolumab." (PMID 40822998, 2025). "For instance, TIGIT, TIM3 and VISTA expression were downregulated in direct co-cultures with LDHC-silenced cancer cells by 72 h, while CTLA-4 expression was reduced in indirect co-cultures." (PMID 40108668, 2025). "We examined the relationship between EIF5A2 and immune checkpoints using Spearman analysis and found that EIF5A2 was correlated with CD274, PDCD1LG2, and HAVCR2 in the majority of cancers and PDCD1, CTLA4, LAG3, SIGLEC15, and TIGIT in some tumors." (PMID 40964657, 2025). "We noticed a widespread dysregulation of RNA modification enzymes across multiple cancer types, focusing on the regulation of the immune checkpoints CD70, CD80, and TIGIT." (PMID 40565233, 2025). "The mRNA expression profile of six Tex markers, LAG-3, PDCD1, TIGIT, HAVCR2, CXCL13, and LAYN was investigated in pan-cancer." (PMID 40076932, 2025).